LOX (lysyl oxidase)
Diseases named in the same sentence as LOX in open-access papers (continued):
Sharing a sentence is not in itself a finding about the gene and the disease.
gastric cancer (continued). "Of the 10 paired cases used for the evaluation of LOX mRNA and protein expression, 7 (70%) gastric cancer tissues showed at least a four-fold increase in LOX mRNA level compared with the adjacent non-cancerous mucosa." (PMID 23425977, 2013). "The mechanism by which LOX is involved in gastric cancer progression has not been well elucidated in this study." (PMID 23425977, 2013). "Furthermore, understanding the expression patterns of PLOD, LOX, and MMP in relation to tumor architecture may have valuable implications for predicting the severity of early-stage gastric cancer metastasis." (PMID 40906383, 2025). "However, only four studies were pooled to discuss the OR for LOX expression in gastrointestinal cancers and gastric cancer was not the main focus." (PMID 36202905, 2022). "Finally, it can be mentioned that, with the help of continuous bioinformatics analyses, BGN, LOX, MMP-9, SERPINE1, and TGFB1 proteins enhance the progression of gastric cancer; they play a significant role in the organization and communication of cells in the extracellular matrix." (PMID 34054953, 2021). "Simultaneously, we examined the expressions and activities of MMP-2 and MMP-9 after LOX inhibition and exogenous LOX treatment in gastric cancer cells, and analyzed the effect of LOX inhibition on PDGFR in the PDGF-PDGFR signaling pathway in gastric cancer cells." (PMID 31777578, 2019).
glioma (41 papers, 2011 to 2025). A benign or malignant brain and spinal cord tumor that arises from glial cells (astrocytes, oligodendrocytes, ependymal cells). "For example, the polymorphisms in LOX gene, 22 G/C and 473 G/A, were associated with increased susceptibility to glioma." (PMID 32424143, 2020). "The mechanism is dependent by PTEN deficiency promoting lysyl oxidase (LOX) expression, a potent macrophage chemoattractant in glioma cells." (PMID 32708484, 2020). "Overexpressed SRC and AKT in PTEN-deficient glioma cells induce the activation of the yes-associated protein 1 oncogene and subsequently, lysyl oxidase (LOX)." (PMID 32984016, 2020). "Recently, it was demonstrated that HIF-1α-responsive genes essential for cell growth, including LOX, were underexpressed in gliomas with IDH1 mutation." (PMID 25790191, 2015). "Furthermore, PTEN deficient glioma cells have been shown to secrete lysyl oxidase (LOX), which recruits macrophages to the tumor." (PMID 34503065, 2021). "For instance, phosphatase and tensin homolog (PTEN) deficiency in glioma drives macrophage infiltration via up-regulation of lysyl oxidase (LOX) and in mesenchymal GBMs neurofibromin 1 (NF1) deficiency results in increased GAM infiltration compared with proneural or classical subtypes." (PMID 33802571, 2021). "Univariate and multivariate analysis of the correlation of LOX expression with OS among glioma patients." (PMID 40270974, 2025). "Knockdown of LOX genes impaired glioma cell functions, induced apoptosis, and altered immune cell behavior by reducing M2 macrophage polarization and enhancing CD8+ T cell activity." (PMID 40270974, 2025). "The downregulation of LOX is unexpected, given its established role in enhancing glioma invasiveness via extracellular matrix crosslinking and remodeling through enhancing epidermal growth factor receptor (EGFR) signaling." (PMID 40835683, 2025). "The lysyl oxidase (LOX) family, a group of copper-dependent amine oxidases, has been implicated in the progression of various cancers, but its specific role in glioma and its relationship with immune infiltration remains insufficiently explored." (PMID 40270974, 2025). "LOX enhances the invasive ability of glioma cells by promoting the crosslinking and remodeling of the extracellular matrix." (PMID 40270974, 2025). "Studies have shown that the expression levels of LOX are significantly higher in glioma tissues compared to normal brain tissue and are positively correlated with the malignancy of the tumor." (PMID 40270974, 2025). "In glioma cells, PTEN deficiency fosters activation of yes-associated protein 1 (YAP1), which modulates the protein-lysine 6-oxidase (LOX)." (PMID 34687436, 2022). "For example, it has been demonstrated that LOX functions as a macrophage chemoattractant to facilitate glioma progression via activating PYK2 signaling." (PMID 36160460, 2022). "Regulation of ECM stiffness and glioma cell migration by LOX expression have been shown in drosophila and mouse models, and LOX activity was reduced by HIF-1α knockdown." (PMID 36076905, 2022). "Tumor-infiltrating macrophages that secrete phosphoprotein 1 (SSP1) were increased via LOX activation, supporting glioma cell growth and angiogenesis." (PMID 34687436, 2022). "Analysis of the survival of patients with glioma expressing LOX or COL1A1 indicated that high expressions of these genes correlated with poor outcomes." (PMID 35908277, 2022). "Clinically, high expression of CD40L, clusters of differentiation 40 (CD40) and LOX correlated with poor survival in patients with glioma." (PMID 35908277, 2022). "Then, LOX recruits macrophages to infiltrate into glioma cells by binding to β1 integrin on macrophages, which secretes SPP1 to support the growth of gliomas." (PMID 33224886, 2020). "Therefore, we developed a novel prognostic model for glioma by integrating LOX/LOXL expression and its co-expressed genes." (PMID 40186284, 2025).
glioma (continued). "In addition, LOX has an excellent predictive value for chemotherapy, immunotherapy, and prognosis in patients with glioma." (PMID 40396123, 2025). "Lysyl oxidase is closely related to the progression of glioma." (PMID 37891828, 2023). "In glioma research, the increase of LOX protein expression is positively associated with the malignant grade of astrocytomas and GBM with IDH1 mutation always exhibits lower LOX expression levels compared with the wild type group." (PMID 36160460, 2022). "In repo>dEGFRλ,dp110CAAX flies, glia-specific knockdown of four genes essential for glial metabolism [ALDOA (Aldolase in flies), ACAT1 (CG8112), ELOVL6 (Baldspot), and LOX (Lox)] partly rescued glioma-induced phenotypes such as shorter lifespan and bigger tumor size." (PMID 36091180, 2022). "Previous studies have shown that LOXL2, a member of the lysyl oxidase (LOX) family, not only promotes glioma cell proliferation, migration, and invasion and induces the epithelial-to-mesenchymal transition (EMT) process but also reduces the sensitivity of glioma cells to temozolomide (TMZ)." (PMID 36588901, 2022). "GM-CSF and lysyl oxidase (LOX) secreted by glioma cells promote TAM recruitment." (PMID 33766119, 2021). "The lysyl oxidase (LOX) family is closely related to the progression of glioma." (PMID 32424143, 2020). "Similarly, survival probability in hepatocellular carcinoma was reliably predicted by a glioma prediction model (ACSL3, ACSL6, ACACA, G6PD, SLC1A5, SLC7A11 and VDAC2) and by a risk model with a strong overlap with the genes in the glioma models (G6PD, HMOX1, LOX, SLC7A11, STMN1/Stathmin 1)." (PMID 34926298, 2021). "PTEN deletion in gliomas activates YAP1, which upregulates LOX expression, leading to macrophage recruitment to the tumor microenvironment through the β1 integrin-PYK2 pathway, enhancing glioma survival and angiogenesis." (PMID 41551155, 2025). "Notably, the elevated expression of the LOX gene, along with a higher presence of M0 macrophages in the high-risk score group, supports the idea that IL7R may contribute to creating an immunosuppressive environment in gliomas." (PMID 40165301, 2025). "The results indicated that members of the LOX family, including LOX, LOXL1, LOXL2, LOXL3, and LOXL4, exhibited high expression levels in glioma cells in comparison to normal human glial cell lines Heb as well as glioblastoma cell lines T98G and LN-229." (PMID 40270974, 2025). "Overexpression of LOX/LOXL showed a strong correlation with tumor progression and poor survival, particularly in glioma." (PMID 40186284, 2025). "Single-cell RNA-seq analysis of HRGs, including LOX, CP, and IGFBP2, was conducted across three distinct glioma datasets." (PMID 38339384, 2024). "Furthermore, glioma stem cells recruited monocyte-derived macrophages by secreting CSCs-derived periostin, thereby supporting tumor growth 50; additionally, the loss of PTEN and NF1 in glioma stem cells upregulated LOX and chemokines, respectively, to attract TAMs 51,52." (PMID 39479456, 2024). "LOXL2 and LOXL3, members of the lysyl oxidase (LOX) family, LOXL2 was found to promote glioma progression, and improve the TMZ resistance of glioma cells." (PMID 36856182, 2023). "Quantitative PCR and immunohistochemical analysis showed that LIF, LOX, MMP9, S100A4, SRPX2, and TIMP1 were expressed at high levels in glioma, whereas SLITI1 and SMOC1 were expressed at low levels, consistent with our previous results." (PMID 36560848, 2023). "Experimental results revealed that expressions of LOX, LOXL1, LOXL2, and LOXL3 were higher in glioma cell lines at mRNA and protein levels." (PMID 36160460, 2022). "The experimental results in our present work demonstrated the elevations of LOX, LOXL1, LOXL2, and LOXL3 in various glioma cell lines." (PMID 36160460, 2022).
glioma (continued). "Considering some previous investigations illustrating that LOXs, especially, LOX, LOXL1, and LOXL4 are closely associated with immunity, finally contributing to tumor progression, we would like to explore whether LOXs expressions were correlated with glioma immunity." (PMID 36160460, 2022). "It has been found that glioma cells with PTEN gene deletion can activate transcription factor YAP1, which can lead to a large amount of LOX excretion." (PMID 33224886, 2020). "Previous glioma studies that manipulated collagen-modifying enzymes, including PLOD2 and LOX knockdown, demonstrated similar results." (PMID 29644003, 2018). "As a control, in the U87 glioma cells we also measured the overexpression of the CA9 (carbonic anhydrase IX), HIG2 (hypoxia-inducible gene-2) and LOX (lysyl oxidase) genes that have been reported to be overexpressed by hypoxia." (PMID 21655185, 2011). "In addition, the data on the survival rate of patients with glioma from the REMBRANDT study and TCGA GBM databases showed that high expressions of LOX and COL1A1 correlated with low survival rate." (PMID 35908277, 2022). "Furthermore, LOX is also identified as a potent macrophage chemoattractant via activating β1 integrin-dependent PYK2 signaling, finally promoting glioma progression." (PMID 36160460, 2022). "Finally, RT-qPCR and Western blot analysis were carried out to validate the mRNA and protein levels of LOXs including LOX, LOXL1, LOXL2, LOXL3, and LOXL4 in glioma cells (T98G and A172) and the normal cell line (HEB)." (PMID 36160460, 2022). "The results indicated that the mRNA and protein expressions of LOX, LOXL1, LOXL2, and LOXL3 were significantly upregulated in these glioma cells than in HEB cell line while the expressions of LOXL4 at mRNA and protein level were not determined in these cell lines (data not shown)." (PMID 36160460, 2022). "In the present study, a progressive increase in levels of LOX, LOXL1, and LOXL3 expression was observed for LGG-IDHmut, LGG-IDHwt, and GBM in the TCGA glioma RNAseq dataset, suggesting their role in determining ECM composition and stiffness enhancement in these phenotypes." (PMID 36076905, 2022). "Additionally, experimental results also revealed that expressions of LOX, LOXL1, LOXL2, and LOXL3 were higher in glioma cell lines (T98G and A172) at mRNA and protein levels compared with the normal astrocyte HEB." (PMID 36160460, 2022). "In addition, GBM promotes macrophage infiltration by up-regulating LOX, which secretes SPP1 to stimulate angiogenesis in the PTEN-knockout GBM xenograft mouse model to sustain the growth of glioma cells." (PMID 33224886, 2020). "Finally, the discovery of sex-biased chromosomal alterations, including LoX, suggests that CIN pathways in glioma may be modulated by sex chromosome dosage, XCI escape, and sex-specific selective pressures." (PMID 41282088, 2025). "Gliomas help recruit TAMs to the TME by secreting various chemokines, including monocyte chemoattractant proteins (MCP-1/CCL2 and MCP-3), C-X-C motif chemokine 12 (CXCL12), colony-stimulating factor 1 (CSF-1), lysyl oxidase (LOX), and glial cell-derived neurotrophic factor (GDNF)." (PMID 38254796, 2024). "M2 macrophages may promote tumor progression and poor prognosis by inhibiting CD8+ T cell function.Numerous studies have shown that various chemokines, including CCL2, CXCL12, LOX, MCP-3, and M-CSF, are secreted by glioma cells to attract M2 macrophages and change their phenotypes." (PMID 37766864, 2023). "Therefore, we speculated that PLOD2, a critical factor that promotes collagen cross-linking and acts upstream of LOX, may also activate the FAK pathway, in order to promote cell invasion in glioma cells." (PMID 28423580, 2017).
colorectal cancer (38 papers, 2013 to 2026). A primary or metastatic malignant neoplasm that affects the colon or rectum. "Enhanced LOX expression in colorectal cancer tissue compared to adjacent colon, with a positive association between LOX expression and disease stage, has been reported by these studies." (PMID 35054220, 2021). "In this study, we explored the prognostic impacts of HIF-1α, LOX and ITGA5 expression in the tumor microenvironment and their relationship with KRAS/NRAS/BRAF mutation status in colorectal cancers." (PMID 39857068, 2025). "Recent studies have highlighted the impact of LOX in colorectal cancer, where it promotes the proliferation of colorectal cancer cells by modulating Src phosphorylation." (PMID 39247609, 2024). "In colorectal cancer, nucleus-accumulated Hic-5 induces expression of LOX that catalyzes crosslinking of collagen fibers to increase ECM stiffness." (PMID 37156857, 2023). "The copper-enzymes LOX (Lysyl Oxidase) promotes adhesion and metastasis of colorectal cancer by affecting the turnover of the Extracellular Matrix (ECM)." (PMID 36684237, 2022). "LOX also plays an important role in the stiffness of colorectal cancer, as LOX-overexpressing colorectal cancer cells increase collagen crosslinking and, as a result, stiffen tumor tissues." (PMID 35205794, 2022). "Recent studies in mouse colorectal cancer models showed enhanced proliferation in LOX-overexpressing cell lines, and the opposite effects in LOX silenced cell lines." (PMID 35054220, 2021). "LOX has been implicated in the inhibition of β-catenin signaling in some cancers, and COL1A1 appears upregulated in colorectal cancer tissues and promotes metastasis via Wnt signaling." (PMID 34638991, 2021). "LOX is upregulated by hypoxia, and in a colorectal cancer model, LOX induced cancer progression via activation of SRC signaling." (PMID 29896451, 2018). "LOX can also promote the progression of colorectal cancer by activating the phosphoinositide 3-kinase-Akt signaling pathway." (PMID 28036074, 2016). "Numerous studies have highlighted the role of LOX as a marker of tumor progression and metastasis, such as in bronchogenic carcinoma and in breast cancer, colorectal cancer, and ovarian cancer." (PMID 25060181, 2014). "A direct relationship between LOX crosslinking and matrix stiffness has recently been demonstrated for the pathological microenvironment of colorectal cancer in liver tissue." (PMID 23782569, 2013). "It has been shown that HIF-1α-inducible lysyl oxidase activates HIF-1α via PI3K/AKT pathway in colorectal cancer." (PMID 23545606, 2013). "More recently, reduced LOX expression has been reported to occur in lung and pancreatic cancer and during malignant progression of prostate and colorectal cancers." (PMID 23750284, 2013). "Moreover, the overexpression of LOX in colorectal cancer cells triggers the production of interleukin-6 (IL-6), which in turn activates the signal transducer and activator of transcription 3 (STAT3) signalling pathway." (PMID 39247609, 2024). "However, LOX overexpression was reported in different types of cancer cell lines, e.g., colorectal cancer, primary clear cell renal cell carcinoma, esophageal squamous cell carcinoma, and ovarian cancer cell lines-OVCAR3 and SKOV-3." (PMID 30583585, 2018). "In phase II, we focused on five HIF-coding genes (HIF1A, HIF1B, HIF2A, HIF2B and HIF3A) and two hypoxia-inducible genes (LOX and CXCL12) and investigated the relationship of their SNPs (n = 77) with the risk of outcome in an additional colorectal cancer patient cohort (n = 535)." (PMID 25405996, 2014).
colorectal cancer (continued). "Elevated ATP7A expression protects KRAS-mutant colorectal cancer cells from copper toxicity, whereas ATP7A silencing reduces LOX activity and inhibits lung cancer metastasis in mice." (PMID 41480765, 2026). "Evidence from a meta-analysis study revealed a significantly high serum LOXL 2 concentration in patients with colorectal cancer (CRC), attributed to increase in Lysyl oxidase-dependent catalytic activity." (PMID 35054220, 2021). "LOX activated by HIF-1α can further induce HIF-1α through PI3K/AKT signaling, a process that involves LOX-generated H2O2 promoting colorectal carcinoma cell proliferation and in vivo tumor growth." (PMID 32708046, 2020). "LOX overexpression enhances cell proliferation and tumor angiogenesis in oral squamous cell carcinoma (OSCC), colorectal cancer (CRC), and astrocytomas." (PMID 28036074, 2016). "More recently, there has been great interest in the role of the enzyme lysyl oxidase (LOX) in driving metastasis in epithelial cancers such as breast and colorectal cancer." (PMID 26077591, 2015). "In the first phase, 49 SNPs from six hypoxia pathway genes (HIF1A, HIF1B, HIF2A, LOX, MIF and CXCL12) in 272 colorectal cancer patients were analyzed." (PMID 25405996, 2014).